CASP8 (caspase 8)
Diseases named in the same sentence as CASP8 in open-access papers (continued):
Sharing a sentence is not in itself a finding about the gene and the disease.
lung carcinoma (72 papers, 2007 to 2025). "Polymorphisms in CASP8 have been associated with the risk of developing a variety of diseases, including gastrointestinal, digestive, colorectal, breast, and lung cancers." (PMID 39605941, 2024). "Apoptosis was linked to caspase 8 activation, and it was controlled by survivin as well as p21 expression in lung cancer cells." (PMID 39200243, 2024). "Loratadine use is linked to enhanced survival in lung cancer patients, potentially due to its role in modulating the interplay between apoptosis and pyroptosis via caspase-8." (PMID 38163866, 2024). "The relationship between CASP-8 gene polymorphisms and the pathogenesis of many cancers, including lung cancer, is well documented." (PMID 33800294, 2021). "Our findings suggest that the rs3769818 CASP-8 polymorphic variant may be a genetic factor predisposing to the development of lung cancer." (PMID 33800294, 2021). "The previous study demonstrated that combination use of TRAIL and Btz could dramatically activate CASP-8 and cause apoptosis in the lung cancer cell line through enhancing the surface expression of TRAIL receptor." (PMID 33392195, 2020). "Numerous studies investigated whether variation in the CASP8 gene region alters cancer risk, including cancers of lung, breast, pancreas, non-Hodgkin lymphoma, head and neck." (PMID 28542283, 2017). "Knocking down Xb130 with siRNA in thyroid or lung cancer cells reduced cell survival, increased susceptibilities of cells to extrinsic and intrinsic signal-induced cell death, which was associated with increased cleavage of caspase-8 and caspase-9." (PMID 27029000, 2016). "Another study reported that autophagy blockade by HCQ significantly increased apoptosis in lung cancer cells by activating both the extrinsic (FOXO3a/FasL/caspase-8) and intrinsic (caspase-9) apoptotic pathways." (PMID 41303490, 2025). "ANGPTL4 is known to promote gefitinib resistance in lung cancer by regulating the NLRP3/ASC/Caspase 8 pathway." (PMID 38731835, 2024). "Combined treatment with the Cox-2 inhibitor niflumic acid and the PPARγ ligand ciglitazone induces ER stress/caspase-8-mediated apoptosis in human lung cancer cells." (PMID 39456799, 2024). "The gain of IGF1R in PRKCSH-deficient cells increased caspase-8 phosphorylation and Mcl-1 expression levels, whereas IGF1R knockdown reduced caspase-8 phosphorylation and Mcl-1 expression levels in lung cancer cells." (PMID 38200153, 2024). "Caspase-8 phosphorylation was significantly increased by TRAIL treatment in lung cancer cells; however, it was almost completely inhibited by PRKCSH depletion." (PMID 38200153, 2024). "In the present study, the anti-apoptotic effects of various pan-caspase, caspase-3, caspase-8, and caspase-9 inhibitors were investigated in PG-treated Calu-6 and A549 lung cancer cells in relation to changes in ROS and GSH levels." (PMID 35889456, 2022). "For lung cancer, we found three cancer driver genes (HLA-A, CASP8 and LEMD2) and two CGC genes (HLA-A and CASP8) among the unreported genes, and one cancer driver gene (HLA-B) and one CGC gene (FGFR1OP) among the previously reported genes." (PMID 36402776, 2022). "The synthetic Chalcone 9X is an aromatic ketone, which has been proved to own antitumor activities in lung cancer cells and hepatic cancer cells through activating Caspase-3 and Caspase-8 signaling pathway." (PMID 35978634, 2022). "Among the demographic and clinical factors, only distant metastases, smoking status, and a family history of malignancy (including lung cancer) were significantly related to the incidence of individual CASP-8 gene genotypes." (PMID 33800294, 2021). "In the conducted study, we observed that carriers of the GG rs3769818 genotype of CASP-8 were more often smokers (p < 0.0001) and those with a history of cancer in the family (any neoplasm: p = 0.0003; lung cancer: p = 0.0157)." (PMID 33800294, 2021).
lung carcinoma (continued). "Previous studies have shown that HCT extract induces apoptosis in various cancer cell types, including human lung cancer A549 cells, by activating caspase-8 and caspase-3." (PMID 34298624, 2021). "In the literature, there are single reports presenting SNPs of the CASP-8 gene as prognostic factors in lung cancer patients." (PMID 33800294, 2021). "Casticin, a flavonoid compound from Vitex rotundifolia induced apoptotsis in human lung cancer cell line H157 depending on the activation of both caspase -8 and -9." (PMID 31870094, 2019). "We identified two new loci (rs3769823, rs10931936) mapping to a genomic region harboring CASP8 which associated with risk of both ESCC and lung cancer of Chinese Han." (PMID 28542283, 2017). "In line with a requirement for caspase-8, FADD deficiency entirely abrogated TRAIL-induced cytokine secretion in human and murine lung cancer cells." (PMID 28212753, 2017). "High linkage disequilibrium SNPs, which map to a region including CASP8, ALS2CR12 and TRAK2, identified as high-risk SNPs in Chinese esophageal cancer, showed significant associations with the increased risk of lung cancer." (PMID 28542283, 2017). "Human CES2 also has the ability to catalyse the hydrolysis of retinyl palmitate to retinol and retinoic acid has been found to induce the expression of TNF receptors, TRAIL and caspase-8 in lung cancer cells resulting in acceleration of TNFa-induced apoptosis." (PMID 29178829, 2017). "Treatment with tumor necrosis factor-alpha (TNF-α) enhanced apoptosis in SAHA-treated lung cancer cells through caspase-8 and caspase-9 activations." (PMID 28099148, 2017). "The caspase-8 inhibitor or TRAIL/DR5 siRNA knockdown alleviated ONC201’s cytotoxicity against lung cancer cells." (PMID 27626799, 2016). "Recent data suggest that deletion or silencing of caspase-8 gene occurs extremely infrequently in cancers, while increased expression of caspase-8 has been documented in lung cancers." (PMID 27101103, 2016). "Furthermore, the ability of curcumin to activate caspase-8 in melanoma, and caspase-3 in hepatocellular carcinoma, neuroblastoma, linfoma and lung cancer cells confirmed its pro-apoptotic role." (PMID 36675194, 2023). "Therefore, the activation of caspase-3, caspase-8, and caspase-9 together appears to be necessary for the complete induction of apoptosis in PG-treated lung cancer cells." (PMID 35889456, 2022). "Compared to paired normal lung tissues, the expressions of GSDME, caspase-3, and caspase-8 were significantly were increased in most lung cancer tissues, and GSDME was mainly found in the cytoplasm and a small amount in the cell membrane in lung cancer tissues." (PMID 36523974, 2022). "Researches revealed that Chalcone 9X could induce cell apoptosis and inhibit invasion and migration capacities through activating Caspase-3 and Caspase-8 signaling pathways in lung cancer cells and hepatic cancer cells in vitro and in vivo." (PMID 35978634, 2022). "Thus, leads to caspase-8 and caspase-3 activation and resulting in the induction of apoptosis in human lung cancer A549 cells." (PMID 35223403, 2021). "The role of caspase 8 in the pathogenesis of lung cancer is unclear." (PMID 33800294, 2021). "The activation of extrinsic apoptosis evidenced with the reduction of c-FLIP and caspase-8, as well as the modulation of intrinsic apoptosis signaling proteins including Bax and Mcl-1 were observed via Western blot analysis in lung cancer cells cultured with colicin N (10–15 μM) for 12 h." (PMID 32069989, 2020).
lung carcinoma (continued). "According to our in vitro data, we speculate that BEL is capable of inducing apoptosis in human A549 lung cancer cells by upregulating the levels of caspase-8/3, reducing the level of PARP1, and ultimately, interfering into STAT3/COX-2 pathways." (PMID 33299414, 2020). "The Lobocrassin B–induced cell death on the human lung cancer cell lines, as evidenced by a decrease in cell viability, and an increase levels of ROS, as well as the activation of caspase-8 and induction of mitochondrial apoptotic pathway, revealed the possible mechanisms involved." (PMID 29207557, 2017). "In conclusion, this study demonstrated that HCT has anti-lung cancer activity by modulating G0/G1 arrest and stimulating the Fas/CD95 protein level, which leads to caspase-8 and caspase-3 activation resulting in the induction of apoptosis in human lung cancer A549 cells." (PMID 23506616, 2013). "In the present study, we observed a significant negative association of cytoplasmic caspase-8 with grade of ccRCCs; cytoplasmic caspase-8 was highest in low-grade tumors, in contrast to previous studies in breast and lung carcinomas." (PMID 19222834, 2009). "Among the genotypes possibly associated with lung cancer risk were Val318Leu of the CASP-5 gene (OR = 2.47, 95% CI: 1.07–5.69, p = 0.03), Lys441Arg of the DR4 gene (OR = 1.89, 95% CI: 1.05–3.40, p = 0.03), and His302Asp for CASP-8 (OR = 2.26, 95% CI: 1.18–4.31, p = 0.02)." (PMID 33800294, 2021). "Activation of TLR3 by dsRNA recruits caspase 8 to form a death-signalling complex in the presence of RIP1, which appears not to be stringently dependent on Fas-associated with death domain (FADD) and results in initiation of the extrinsic apoptosis pathway in lung cancer cells." (PMID 28790362, 2017). "To evaluate whether CGP57380 enhances antitumor efficacy of RAD001 on lung cancer cells through inducing cell apoptosis, we firstly detected the expression level of cleaved-caspase-8 (c-caspase-8) and PARP (c-PARP) in the lung cancer cells treated with CGP57380 and RAD001." (PMID 27050281, 2016). "Our qRT-PCR results indicated that Odo A treatment led to upregulation of CASP3, CASP7, CASP8, and CASP9 expression, which suggests that the extrinsic route was responsible for blocking the development of lung cancer cells." (PMID 40141789, 2025). "Multiple under-expressed proteins were also predictable to a great extent, the top-performing ones being CASP8, MET, BCL2, and SETD2 in BRCA; AR and TFRC in gastric cancer; and VHL in lung cancer with AUCs ranging 0.814–0.866." (PMID 38491101, 2024). "We found that the expression of up‐regulated hub DEAMGs BCL2L1, CASP8, SIRT1 and CCL2 in lung cancer tissues with high metastasis was dramatically increased compared with lung cancer tissues with low metastasis." (PMID 37850256, 2024). "Further, ONC201 induced exogenous apoptosis activation in lung cancer cells, which was evidenced by TRAIL/death receptor-5 (DR5) induction and caspase-8 activation." (PMID 27626799, 2016). "Similar results were also obtained in H460 and primary human lung cancer cells (“Pat-2”), where TRAIL plus DR5 siRNA knockdown or caspase-8 inhibition (z-IETD-fmk) significantly alleviated ONC201’s cytotoxicity." (PMID 27626799, 2016). "FnIII-1c inhibited TRAIL-induced activation of caspase 8 and subsequent apoptosis in NCI-H460 lung cancer cells." (PMID 27484721, 2016). "Celecoxib was observed to induce lung cancer cell apoptosis by the intrinsic and extrinsic apoptosis pathways, including mitochondrial apoptosis pathway and FADD- and caspase-8-dependent death mechanism." (PMID 27007231, 2016).
lung carcinoma (continued). "G31P also enhanced apoptosis in lung cancer cells as determined by elevated levels of cleaved PARP, Caspase-8, and Bax, together with a reduced expression of the anti-apoptotic protein Bcl-2." (PMID 26087179, 2015). "Half of them correspond to various phenotypes of cancer (e.g., leukemia, lung cancer and adrenal cortical carcinoma) based on the information retrieved from OMIM database, including several well-studied carcinogenesis genes (Bcl2, Casp8, Fas)." (PMID 24565050, 2013). "Moving to our results we found that the treatment of the A549 human lung cancer cell line with ALUP, BA, and LUP significantly increased the mRNA expression of the apoptotic promotors Bax (the pro-apoptotic), CASP-8, and CD95, with BA treatment showing the most pronounced effect." (PMID 37845669, 2023). "When lung cancer cells were treated with ATO/VPA, cleaved forms of caspase-8 and caspase-9 were increased, implying that caspase-8 linked with the cell death receptor (extrinsic) pathway was activated in these cells, and caspase-9 related to the mitochondrial (intrinsic) pathway was also activated." (PMID 32290325, 2020). "Since caspase-8 activation and TRAIL expression are characteristic markers of extrinsic apoptosis pathway activation, we next tested apoptosis activation in ONC-treated lung cancer cells." (PMID 27626799, 2016). "The data showed that PTL could induce cleavage of apoptotic proteins such as CASP8, CASP9, CASP3 and PARP1 both in concentration- and time-dependent manner in tested lung cancer cells, indicating that apoptosis was trigged after PTL exposure." (PMID 24387758, 2014). "We also demonstrated that high doses of PL elicit a caspase cascade in human and murine lung cancer cells, but not in normal lung epithelial cells, in which caspase 3, caspase 8 and BID are activated." (PMID 17262078, 2007). "Notably, we found that juglanin could induce both intrinsic and extrinsic pathways to enhance apoptotic response in lung cancer cells, proved by the elevated Bad/Bax/Caspase-9 and TRAIL/FADD/Caspase-8, respectively." (PMID 29212196, 2017). "Knocking down BNIP3 with transfection reagent, then we extracted proteins and detected GSDMD and caspase-8 by western blot, and the results showed that knocking down BNIP3 increased GSDMD and caspase-8, indicating that knocking down BNIP3 could induce pyroptosis in lung cancer cells H358." (PMID 36092153, 2022).
colorectal cancer (70 papers, 2002 to 2026). A primary or metastatic malignant neoplasm that affects the colon or rectum. "CASP8 somatic mutations have been identified in several types of cancers including colorectal cancer, gastric cancer, and head and neck cancer." (PMID 36533709, 2023). "Inactivation and somatic mutation of CASP8 are reported in various cancers, and a recent report found a colorectal cancer patient with somatic loss of heterozygosity in CASP8." (PMID 37234870, 2023). "Smac mimetics have been shown to induce necrosis in caspase-8-deficient colorectal cancer cells, inhibiting tumor growth and proliferation in mouse colorectal cancer models." (PMID 37989855, 2023). "Smac mimetic can induce necroptosis in caspase-8-deficient colorectal cancer cells, thereby impeding the growth and proliferation of cancer cells in a mouse colorectal cancer model." (PMID 35330731, 2022). "It was discovered that this mode of cell death was activated in caspase-8 deficient colorectal cancer and led to the significant tumor regression in mice in response to Smac mimetic." (PMID 34437575, 2021). "Our study with a large sample size provides additional evidence of the association between CASP8 -652 6N ins/del polymorphism and colorectal cancer risk." (PMID 30057371, 2019). "We aimed to discern potential association of these two variants and rs113686495 (CTGTCATT/−), as well as CASP8 mRNA and protein expression levels with colorectal cancer (CRC) in Han Chinese." (PMID 23844036, 2013). "Haplotypes of the CASP8 gene promoter variants in Han Chinese with colorectal cancer and healthy individuals." (PMID 23844036, 2013). "CASP8 is often mutated or epigenetically suppressed in colorectal cancer." (PMID 40422233, 2025). "However, previous studies showed that inactivating mutations of the caspase-8 genes are rare in human colorectal carcinomas." (PMID 32102251, 2020). "For example, a Caspase-8 (CASP8) polymorphism has been associated with reduced susceptibility to multiple cancers while low-penetrence CRC susceptibility loci have been shown to increase the risk of developing colorectal cancer in Lynch syndrome patients." (PMID 23675233, 2011). "Collectively, these findings establish that atorvastatin and rosuvastatin engage the extrinsic apoptotic pathway through caspase-8 activation, with rosuvastatin demonstrating superior potency in both colorectal cancer models examined." (PMID 41596561, 2026). "Taken together, our results indicated that chemotherapy sensitizes colorectal cancer to release ATP via the caspase-8/3-mediated cleavage of PANX1 downstream of TNFα." (PMID 38195677, 2024). "The PI3K/Akt/NFκB pathway is known to protect colorectal cancer cells from apoptosis by reducing the activity of caspase-8 and caspase-3." (PMID 39839775, 2024). "Here, we show that TNFα sensitizes colorectal cancer promote the release of ATP by caspase-8/3-mediated PANX1 cleavage via TNFR1 during chemotherapy-induced cell death." (PMID 38195677, 2024). "By inhibiting the activities of caspase-8 and caspase-3, the NFκB pathway is known to shield colorectal cancer cells from apoptosis promoting cell survival and resistance to apoptosis." (PMID 39839775, 2024). "Curcumin induces apoptosis in colorectal cancer cells via altering the Fas-regulated extrinsic pathway, activating caspase 8 and TRAIL binding to death receptors (DR), and upregulating DR5 proteins." (PMID 39770516, 2024). "A significant decrease in caspase-9 activity and concomitant overexpression of caspase-8 was found in tissues obtained from patients with colorectal cancer compared to tissues obtained from healthy individuals." (PMID 33919909, 2021). "Activation of caspase-8 and caspase-9 led to activation of caspase-3, caspase-6, and caspase-7 and resulted in apoptosis of colorectal cancer cells." (PMID 33953834, 2021).